IL17A (interleukin 17A)
Diseases named in the same sentence as IL17A in open-access papers (continued):
Sharing a sentence is not in itself a finding about the gene and the disease.
cancer (continued). "The median IL17A level in healthy participants was 7.09 pg/mL, whereas the median level in cancer patients was 26.05 pg/mL, indicating that IL17A is a marker of cancer risk." (PMID 38398137, 2024). "The levels of interleukin 8 (IL8) and interleukin 17A (IL17A) were measured in the serum samples of cancer patients and healthy individuals." (PMID 38398137, 2024). "Conversely, the absence of IL-10 amplifies cellular proliferation, resulting in an elevated frequency of IL-17+ γδ T cells and an increased level of IL-17A in murine malignant tumors (MPEs)." (PMID 39253082, 2024). "Interleukin (IL)-17A is a proinflammatory factor and exerts a vital function in inflammatory diseases and cancers." (PMID 38430256, 2024). "The levels of IL8 and IL17A were higher in the cancer group, while the level of IL33 was higher in the healthy group." (PMID 38398137, 2024). "Then, the impacts of these macrophages and IL-17A in the malignant phenotype of cancer cells were assessed." (PMID 38430256, 2024). "These agonists exerted control over cancer cell growth by promoting the infiltration of T17 cells, which, in turn, upregulated the expression of IL-17A while downregulating PD-L1 expression." (PMID 38607733, 2024). "Interleukin-17 A (IL-17A) is one of the most intensively investigated interleukins from the IL-17 family which play a critical function in cancer development, progression, and control." (PMID 38816694, 2024). "One of the factors that distinguishes cancer patients from healthy individuals is the level of IL17A in their blood." (PMID 38398137, 2024). "Upon re-examining of The Cancer Genome Atlas data, we observed a weak but significant correlation between ALDH2 and the IL-17A gene in certain types of cancers." (PMID 38226171, 2024). "Th-17 cell infiltration with a common pro-inflammatory signature cytokine, IL-17A, is a crucial player in the proliferation, growth, migration, and dissemination of many cancer cells, including BC and many more types of cancer." (PMID 36993955, 2023). "The release of lactate dehydrogenase (LDH) and IL-1β into the supernatant of cancer cells following stimulation was increased with IL-17A treatment." (PMID 37211606, 2023). "There was a correlation between the ECE of the lymph node and the percentage of IL-17A-positive cancer cells in the prostate (p = 0.009), as well as between the intensity of staining IL-17A-positive cancer cells in LN+ (p = 0.014)." (PMID 37760548, 2023). "In cancers, abnormally generated IL-17A through the IL-17R signaling in multiple types of cells promotes disease development." (PMID 37605139, 2023). "It was demonstrated that IL-17A activates certain immune cell types, such as myeloid-derived suppressor cells (MDSCs) and neutrophils to suppress antitumor immunity and promote cancer development." (PMID 37605139, 2023). "There are several preclinical studies showing efficacy of IL-17A antibodies in the treatment of cancer." (PMID 37427128, 2023). "IL-17A–producing γδ T cells not only infiltrate human tumors, but high levels of IL-17A or abundance of γδ T cells also correlates with poor prognosis and metastasis in cancer patients." (PMID 36480166, 2023). "IL-17A promotes cancer growth and progression by directly stimulating cancer cells via activation and translocation of NF-κB, STAT, and AP-1 and signalling that leads to the downstream activation of kinases, such as MAPK and HER1." (PMID 37211606, 2023). "Previous studies have shown higher levels of IL-17A in serum and cancer tissues of patients with GC compared with healthy controls." (PMID 36125689, 2023). "IL-17A and IL-17RA are members of a large family of IL-17 cytokines that have been demonstrated to have both pro-cancer (in most cases) and cancer-inhibiting effects." (PMID 37760548, 2023).
cancer (continued). "In AGS cells, recombinant human IL-17A (rhIL-17A) inhibited apoptosis and G1/S phase transition arrest while promoting reactive oxygen species production, sphere formation ability of cancer stem cells (CSC), and expression of stemness-related genes." (PMID 36125689, 2023). "IL-17A promotes tumorigenesis by upregulating PD-L1 expression in hepatocellular stem cells, helping cancer cells to self-renew and escape immune attack." (PMID 37978543, 2023). "Collectively, these studies underpin the crucial role of lung IL-17A–producing γδ T cells in cancer progression." (PMID 36480166, 2023). "It is well known that HCC is an inflammation-driven cancer, and the significance of IL17A in the proliferation and migration of HCC has been investigated in tissue and mouse models." (PMID 37209815, 2023). "TRAF4 has been reported as a positive regulator for cell growth/proliferation pathways (AKT, ERK1/2, and ERK5) induced by EGF, TGF-β, and IL-17A signaling, contributing to the proliferation and migration of cancer cells." (PMID 37607012, 2023). "We assessed the expression levels of IL-17A and IL-17RA in cancer cells in prostate and, for the first time, also in LN+." (PMID 37760548, 2023). "Th17 cytokine gene IL-17A plays a pivotal role in various infectious diseases, inflammatory and autoimmune disorders, and cancer." (PMID 36685921, 2022). "Chronic inflammation promotes cancer progression by increasing the production of pro-tumorigenic cytokines, mainly IL-6, IL-17A, IL-22 and IL-23, which activate NF-κB and STAT3 signaling pathways." (PMID 35387985, 2022). "The increased cytotoxic gene expression (upregulated Prf1 and GzmB) in T cells found in chemo-sensitive tumors further substantiates the increased anti-cancer activity of IL-17A+ DOX sensitive tumors." (PMID 35924165, 2022). "The usage of IL-17A neutralizing antibodies significantly improved the antitumor activity of anti-VEGF therapies in cancer research." (PMID 35392087, 2022). "The presence of IL-17A has been examined in multiple cancer types and has emerged as an attractive cancer biomarker." (PMID 35924165, 2022). "This abnormal myelopoiesis in cancer and chronic inflammation is induced by several cytokines, including interleukin (IL)-17A, G-CSF, GM-CSF, and TNF (tumor necrosis factor)-α, as well as transcription factor ROR1C." (PMID 36395389, 2022). "The upregulation of these processes was significantly mitigated upon co-administration of IL-17A protein, suggesting that the anti-exhaustion inducing effects are derived from the cancer cells." (PMID 35924165, 2022). "Interactions between the microbiota and IL-17A-producing cells are also involved in the pathogenesis of immune-mediated inflammatory diseases and cancer." (PMID 36078902, 2022). "Extensive studies have shown that IL-17A contributes to the initiation, progression, metastasis, and drug-resistance in diverse types of human cancers." (PMID 36466926, 2022). "Previous reports showed that PD-L1 can be induced in MDS cells by IFNγ and TNFα, although a variety of other factors (i.e., IL-10, FasL, and IL-17A) have been shown to upregulate PD-L1 in other cancer types." (PMID 35992887, 2022). "IL-17A increased anti-cancer phenotypes observed in vitro only upon coadministration with DOX suggesting an alternate function in the presence of chemotherapeutics." (PMID 35924165, 2022). "Cancer cells were found to express the IL-17 receptor (SFigure 2), and therefore to be potential targets of IL-17A signaling." (PMID 35924165, 2022). "Chemotherapy-treated human CAFs promoted cancer-initiating cell self-renewal via IL-17A, and IL-17A was found to be overexpressed in colorectal CAFs in response to chemotherapy, as validated directly in patient-derived specimens without culture." (PMID 35326670, 2022). "As predicted, the concentration of IL-17A was highest in the coculture of immune cells, bacteria, and cancer cells." (PMID 36000726, 2022).
cancer (continued). "In contrast to IL-17A, which has already been studied intensively, IL-17F has thus far received much less attention in the cancer research field." (PMID 35012470, 2022). "Although the mean expression levels of IL6, CXCL8, IL10, and IL17A were higher in the cancer group than those in the control group, the difference was not statistically significant." (PMID 36501012, 2022). "IL-17A plays a role in antiparasitic immunity, and in metastatic colon cancer, one of the most common cancers with liver metastases." (PMID 36077175, 2022). "An increased presence of IL-17A-positive cells and high levels of IL-17A are associated with lymphatic vessel density (LVD), the smoking status, an advanced cancer stage (III/IV), and the poor survival of NSCLC patients." (PMID 33802737, 2021). "Interleukin (IL)-17A secreted by T-helper 17 lymphocytes is a proinflammatory cytokine that plays an important role in cancer pathogenesis." (PMID 33802737, 2021). "Revealing the role of GD3 in inhibiting the production of IL-17A in CTCL would aid the understanding of the suppressive mechanism of the antitumor activity by malignant tumor cells." (PMID 33859643, 2021). "Our results on IL17A are in agreement with a recent study conducted on HPV-related cancer, where Xue and colleagues demonstrated that Th17 cells and IL17A increased in cervical lesions when compared to controls." (PMID 33801021, 2021). "We used RT-qPCR to screen mRNA levels of a variety of inflammatory factors closely related to the development of cancer, including IL-6, IL-10, IL-17A, and Hsp90α, in LINC00673 and control stable cells." (PMID 34094965, 2021). "The cytokines IL-17A contribute to immune response in cancer and is and is secreted from IL-17A-producing CD4+ T cells (Th17 cells), CD8+ T cells, γδT cells, and natural killer T cells." (PMID 34924561, 2021). "CAFs also affects cell-mediated immune resistance in the cancer microenvironment, thus it is necessary to understand the effect of IL-17A using immunocompetent mouse in near future." (PMID 32488650, 2021). "The IL-17 family includes six members, IL-17A, IL-17B, IL-17C, IL-17D, IL-17E (also known as IL-25), and IL-17F, which play a crucial role in autoimmunity, cancer, and other inflammatory conditions." (PMID 33562334, 2021). "As for IL-17A, the role of IL-17B, IL-17C, IL-17D, IL-17E, and IL-17F in cancer remain controversial." (PMID 33244315, 2020). "The regulatory potential of the IL-17 immune axis makes IL-17 a compelling target in cancer immunotherapy." (PMID 33115468, 2020). "We also underscore differences and similarities between IL-17A and IL-17B-to-F in the microbiota-immunity-cancer axis, and we highlight therapeutic strategies that directly or indirectly target IL-17 cytokines in diseases." (PMID 33244315, 2020). "IL-17A from γδ T cells binds to IL-17 receptors and promotes cancer progression via several downstream effects on malignant cells as well as other immune cells." (PMID 32765528, 2020). "The pro-tumorigenic properties of γδ T cells are largely driven by IL-17A, whose expression in γδ T cells is increased in preclinical models for several cancers." (PMID 32765528, 2020). "IL-17A has complex roles in cancer; hence, understanding how to target IL-17A-enriched tumors is of interest scientifically and practically." (PMID 32770025, 2020). "PM2.5-challenged mice with IL-17a knockout exhibited markedly alleviated lung injury and cancer stem cell property." (PMID 32554855, 2020). "Strong correlations have been found between IL-17RA, microbiota, and cancer, and most of them have been attributed to IL-17A." (PMID 33244315, 2020). "IL-17F, the newest member of the IL-17 family that shares the greatest homology with IL-17A, was reported to provide protective effects against several types of cancer, such as oral, colon, and hepatocellular carcinoma." (PMID 31083515, 2019).
cancer (continued). "For example, BIRC5 (also known as Survivin) and BCL2 are anti-apoptotic genes that promote cancer cell survival, whereas IL17A, IL23 and IL6 play important roles in promoting pro-inflammatory oncogenic signaling." (PMID 31292446, 2019). "Firstly, the expression of CCL20 and IL-17A in CRC tissues was significantly higher than that in other cancer tissues." (PMID 31387598, 2019). "Since an opposite effect has been reported for IL-17A (which shares the highest homology with IL-17F) on cancer cells, we also investigated the influence of this cytokine on OTSCC cell proliferation." (PMID 31083515, 2019). "Although its role in cancer has been widely described as pro-tumorous, there also exist studies proving the antitumor effect of IL-17A." (PMID 31159823, 2019). "CCL20 and IL-17A were identified as candidate biomarkers using multiplex assay and pan-cancer screening of TCGA data." (PMID 31387598, 2019). "Since IL-17A is able to inhibit CRC cell apoptosis both in vitro and in vivo, we demonstrated that the reduced IL-17A levels allow effective TNF-α-mediated killing of cancer cells." (PMID 31052449, 2019). "The splenic immunophenotye of mice with advanced cancer showed the emergence of the hyaluronic acid receptor CD44+ and in a smaller extent IL-17A+ MDSCs, the loss of B220+ and CD62L+ B-cells, the loss of CD62L+ CD4+ and CD8+T-cells." (PMID 31881770, 2019). "GLK overexpression in T cells induces production of IL-17A, which promotes cancer cell migration and increases cancer metastasis." (PMID 31640697, 2019). "Study reports indicate that IL-17A is responsible for the aggressive progression of several malignant tumors." (PMID 31387598, 2019). "Injecting recombinant Lactococcus lactis strain secreting IL-17A into a mouse allograft model of HPV-induced cancer effectively prolonged the disease free survival in contrast to control mice treated with the wild type strain of L. lactis." (PMID 31159823, 2019). "Interleukin-17A (IL-17A) has been reported to participate in the pathogenesis of multiple autoimmune diseases and cancers." (PMID 31159823, 2019). "γδ T cells are also a direct and potent source of critical inflammatory cytokines like IFNγ, TNFα and IL-17A in many pathological contexts, including infection, autoimmune disease and cancer." (PMID 30538697, 2018). "Our approach for simultaneously targeting MMP-9 and IL-17A paves the way toward the development of bi-specific inhibitors targeting the MMPs and pro-inflammatory cytokines for the generation of novel cancer therapy agents." (PMID 29983876, 2018). "It was previously shown that IL-17A is associated with an increased expression of MMP-9, leading to enhanced cancer invasiveness and metastasis." (PMID 29983876, 2018). "We evaluated the therapeutic potential of targeting the MMP-9/IL-17A axis, which has been ascribed putative pathobiological roles in various types of cancer." (PMID 29983876, 2018). "Altogether, our results demonstrate that intranasal administration with L. lactis secreting IL-17A results in a partial protection against TC-1-induced tumors in mice, confirming antitumor effects of this cytokine in our cancer model." (PMID 30728820, 2018). "Here, we present a novel strategy for developing cancer therapeutics, based on the simultaneous binding and inhibition of both IL-17A and MMP-9." (PMID 29983876, 2018). "Vδ1 γδ T cells are involved in inflammation-induced cancer progression, dependent on the production of IL-17A." (PMID 29316940, 2018). "It has been found that IL-17A stimulates stem-like cells and promote the development of various types of cancers." (PMID 28484082, 2017). "The adverse correlation between them was found in the tumor milieu; however, in our study the opposite relation was observed: the concentration of IL-17A correlated with Tregs in the lung affected by cancer." (PMID 28470464, 2017).
cancer (continued). "IL-17A can stimulate cancer cell proliferation and IL-17A levels in cancer tissues can be inhibited by cordycepin and CMP." (PMID 29212184, 2017). "We also found that the levels of IL-17A in cancer tissues of control mice were significantly increased, and CMP inhibited these levels." (PMID 29212184, 2017). "More importantly, we demonstrated that circulating level of IL-17A as well as the contents of IL-17A and IL-17RA in local cancer tissues were significantly increased in TSCC patients." (PMID 28035060, 2017). "IL-17A is a pro-inflammatory cytokine mainly produced by activated Th-17 cells and has been shown to play an active role in many cancers." (PMID 28402963, 2017). "More importantly, IL-17A levels were negatively correlated with disease-free survival rates in cancer patients, including HNSCC." (PMID 29212184, 2017). "The roles of IL-17A in cancers are controversial since both pro- and antitumor effects have been reported." (PMID 28035060, 2017). "We observed a significant correlation of the proportion of these cells with IL-17A concentration in the BALF from the cancer milieu." (PMID 27866241, 2017). "Interleukin-17A (IL-17A), a proinflammatory cytokine mainly produced by T helper 17 cells, exerts protumor or antitumor effects in different cancer entities." (PMID 28035060, 2017). "Recently, several studies have shown that IL-17A has either a protumor or antitumor role in different cancer models." (PMID 29029520, 2017). "IL17A had significantly increased peripheral blood and tissues levels from a variety of cancer patients." (PMID 26083022, 2015). "In order to identify the kinases involved in chemoresistance induced by IL-17A and IL-17E pre-treatments, we explored the activation of signaling pathways involved in cancer progression." (PMID 26154409, 2015). "Our results revealed that in HDC−/− mice, there was marked induction by OVA of a number of MC-derived proinflammatory cytokines, including several key cancer-promoting cytokines such as IL-1β and IL-6 and their downstream effector cytokine IL-17a." (PMID 26429861, 2015). "IL-17A has been reported to promote the invasion of cancer cells via upregulating the expression of MMP-2 and MMP-9." (PMID 24905806, 2014). "IL-17A was reported to promote the invasion of cancer cells via up-regulating the expression of MMP-2/-9." (PMID 25244643, 2014). "MMP-2 and MMP-9 play important roles in cancer metastasis, and IL-17A can affect the expression of MMP-2 and MMP-9." (PMID 25244643, 2014). "IL-23A was secreted from both macrophages and GC cells and promoted cancer proliferation through IL-17A/IL-17RA/NF-κB signaling." (PMID 25349535, 2014). "Since overexpression of MMPs can promote cancer metastasis, we next investigated the effect of IL-17A on MMPs expression in GC cell lines." (PMID 24905806, 2014). "MMP2 and MMP9 play important roles for cancer metastasis, and IL-17A can affect the expression of MMP2 and MMP9." (PMID 25250801, 2014). "IL-17A, in particular, plays an important role in cancer development and in inflammatory responses; therefore, we investigated IL-17A and Th17 cell populations." (PMID 25181290, 2014). "Our data obtained with human primary DC cultures delineate future personalized medicine combining anti-IL-17A biotherapy with (VBL- or AraC-based) chemotherapy to counteract cancer cell survival in an IL-17A-rich tolerogenic microenvironment." (PMID 23441221, 2013). "Recently, some review papers providing new insight into Th17 have published, such as human cancer-associated immunity, Th17 expressing CD161 and interleukin-4-induced gene 1; Th17 function markers and humanized anti-IL-17A monoclonal antibody." (PMID 23365685, 2013). "Pearson's correlation demonstrates a strong positive correlation between RORγ and IL-17A with IL-21in both Hp-infected tissues and cancer tissues." (PMID 23365642, 2013). "The role of IL-17A in cancer remains controversial with protumor (pro-angiogenic) versus antitumor (immune) effects." (PMID 23441221, 2013).